ETS1 (ETS proto-oncogene 1, transcription factor)
Diseases named in the same sentence as ETS1 in open-access papers (continued):
Sharing a sentence is not in itself a finding about the gene and the disease.
ovarian carcinoma (continued). "Our results show that Ets-1 mediates enhanced Sxc- activity to increase glutathione recycling in ovarian cancer cells, and that this effect was enhanced during oxidative stress." (PMID 24238102, 2013). "In further support of this theory, our laboratory has previously shown that Ets-1 transcription can be induced by nuclear factor (erythroid-derived 2)-like 2 (Nrf2) in 2008 ovarian cancer cells." (PMID 24280356, 2013). "We have used a tetracycline-inducible Ets-1 overexpression model derived from 2008 ovarian cancer cells in the present study." (PMID 24238102, 2013). "We have previously shown that our Ets-1 ovarian cancer expression model results in changes to cellular metabolism, particularly in the context of glucose utilization and oxygen consumption." (PMID 24280356, 2013). "In this study we have performed various bioinformatic analyses on existing microarray data to further clarify the role of Ets-1 in ovarian cancer, and validated these results with functional assays." (PMID 24280356, 2013). "We have chosen to further characterize the function of Ets-1 in ovarian cancer based on our previous work using the 2008/C13* ovarian cancer model of cisplatin resistance." (PMID 24238102, 2013). "In this study, we have observed the upregulation of GPX1 and 2 protein expression, increased GPX enzyme activity, and decreased intracellular ROS in response to Ets-1 overexpression in ovarian cancer cells." (PMID 24280356, 2013). "More recently, we have established that Ets-1 regulates energy metabolism in ovarian cancer cells by enhancing glycolytic dependence, and also extended these findings to a breast cancer model." (PMID 24238102, 2013). "As Ets-1 is prominently overexpressed in C13* cells, we generated a stable overexpression model of Ets-1 in 2008 cells and have since characterized novel roles for Ets-1 in ovarian cancer cells using this model." (PMID 24238102, 2013). "The Ets1 proto-oncogene is a transcription factor that can act as a “molecular switch” for auto-regulation of the GR promoter, and high ETS1 expression predicts poor prognosis in patients with ovarian cancer." (PMID 22553910, 2012). "In this study we employed IHC to evaluate the expression of Ets-1, Ang-2 and maspin in clinical samples of ovarian cancer." (PMID 21439064, 2011). "The expression of Ets-1, Ang2 and maspin showed close relationship with angiogenesis in ovarian cancer and expression of maspin appeared to be correlated with high grade and MVD." (PMID 21439064, 2011). "The connections among the three angiogenic factors Ets-1, Ang-2 and Maspin need future study and the mechanisms by which these factors crosstalk will provide us new therapeutic interventions for ovarian cancer." (PMID 21439064, 2011). "In the present study, we examined the relationship between the expression of Ets-1 and its targets Ang-2 and maspin in ovarian cancer and their clinical significance." (PMID 21439064, 2011). "Immunohistochemical staining demonstrated that Ets-1 was expressed in vascular endothelial cells and cancer cells of ovarian cancer." (PMID 21439064, 2011). "Microarray analysis of the effects of Ets-1 over-expression in these ovarian cancer cells shows that Ets-1 up-regulates key enzymes involved in glycolysis and associated feeder pathways, fatty acid metabolism, and antioxidant defense." (PMID 21042593, 2010). "To analyze the genomic consequences of Ets-1 over-expression in these ovarian cancer cells, we conducted a human gene microarray." (PMID 21042593, 2010). "A novel function for Ets-1 was elucidated in this study following genomic and functional analysis of an ovarian cancer Ets-1 expression model." (PMID 21042593, 2010). "In this study we have demonstrated that Ets-1 plays a role in the regulation of energy metabolism in ovarian cancer cells." (PMID 21042593, 2010).
ovarian carcinoma (continued). "In ovarian cancer, for example, Ets-1 expression strongly correlates with the degree of angiogenesis in the primary tumor and the development of metastatic lesions." (PMID 20454645, 2010). "Ets-1 was over-expressed in 2008 ovarian cancer cells using a tetracycline-inducible system, generating 2008-Ets1 cells." (PMID 21042593, 2010). "Our microarray analysis determined that Ets-1 is a regulator of antioxidant gene expression in ovarian cancer cells, particularly glutathione peroxidases, which preferentially target H2O2 and lipid hydroperoxides for detoxification." (PMID 21042593, 2010). "In order to determine the functional importance of Ets-1 expression in cancer cell metabolism, we generated the tetracycline-inducible Ets-1 over-expressing ovarian cancer cell line 2008-Ets1." (PMID 21042593, 2010). "Collectively our findings demonstrate that Ets-1 is involved in the regulation of cellular metabolism and response to oxidative stress in ovarian cancer cells." (PMID 21042593, 2010). "These statistics support the overall concept that Ets-1 expression in ovarian cancers contributes to tumor growth and progression that is at least in part mediated by an increase in the degree of angiogenesis." (PMID 20454645, 2010). "Moreover, Gln deprivation reduced the production of matrix metalloproteinases (MMP2 and MMP9) in SKOV3 cells by inhibiting the nuclear translocation of ETS1, thereby diminishing the migratory and invasive capabilities of ovarian cancer cells." (PMID 40276500, 2025). "Similarly, KRT80 regulated by the miR-206/ETS1 axis plays a pivotal role in promoting tumor progression in ovarian cancer through the activation of the MEK/ERK signaling pathway." (PMID 40647481, 2025). "Compared with control exosomes, exosomes derived from ETS1-overexpressing ovarian cancer cells (LV-ETS1 Exos) stimulated the polarization of more macrophages toward the M2 phenotype (CD163 marker), as well as the production of more CXCL5 and CCL2 in macrophages, via integrin αvβ5/AKT/Sp1 signaling." (PMID 36477408, 2022). "The wound-healing assay demonstrated that ETS1 facilitated the migration of ovarian cancer cells." (PMID 36477408, 2022). "Furthermore, exosomes derived from ETS1-overexpressing ovarian cancer cells mediated pro-tumorigenic effects of omental macrophages via the integrin αvβ5/AKT/Sp1 signaling pathway, consequently promoting omental metastasis of ovarian cancer." (PMID 36477408, 2022). "ETS1 − an evolutionarily conserved transcription factor involved in the regulation of a number of cellular processes − is overexpressed in several malignancies, including ovarian cancer." (PMID 34023818, 2021). "We conclude that the GSK3β/ETS1/MMP-9 axis may regulate the biological aggressiveness of ovarian cancer and can serve as a prognostic factor in patients with this malignancy." (PMID 34023818, 2021). "It is conceivable that – in addition to the GSK3β/Snail pathway – the GSK3β/ETS1/MMP-9 axis may be involved in ovarian cancer spread." (PMID 34023818, 2021). "This confirms that ETS1 was the direct target of miR-206 in ovarian cancer cells." (PMID 34659572, 2021). "Finally, we generated a specific antibody against phosphorylated ETS1 and examined its expression levels in human ovarian cancer specimens." (PMID 34023818, 2021). "In conclusion, our study is the first to depict a scenario in which oncolipid (LPA) signaling leads to metabolic plasticity in ovarian cancer cells towards reduced mitochondrial oxidative phosphorylation, as well as increased glycolysis through the pro‐metastatic protein ETS‐1." (PMID 28236660, 2017). "Thereby, LPA‐induced ETS‐1 was found to maintain the invasive potency of ovarian cancer cells in two key aspects, first, by switching the metabolic dependency of the cancer cells towards increased glycolysis, and second, by regulating the expression of MMPs in a cell‐type specific manner." (PMID 28236660, 2017).
ovarian carcinoma (continued). "Thus, our study highlights the phenotypic changes induced by the pro‐metastatic factor ETS‐1 in ovarian cancer cells." (PMID 28236660, 2017). "Furthermore, the bioenergetic status of LPA‐treated ovarian cancer cells mimics hypoxia through induction of hypoxia‐inducible factor‐1α, which was found to transactivate ets‐1." (PMID 28236660, 2017). "Our previous results suggested that promoter hypomethylation, especially around the ETS1 and ETS2 motifs, may be involved in the up-regulation of PARP1 expression in BRCA1-mutated ovarian cancer." (PMID 24448423, 2014). "Interestingly, we have found that several enriched metabolic and oxidative stress pathways are differentially expressed in an ovarian cancer cell model of Ets-1 overexpression." (PMID 24280356, 2013). "Furthermore, Ets-1 is a key regulator of oxidative stress in ovarian cancer cells by mediating alterations in glutathione antioxidant capacity." (PMID 24280356, 2013). "Interestingly, metabolic pathway associations were found using all analysis methods, suggesting that this observation is the most significant finding within our Ets-1 overexpression model of ovarian cancer." (PMID 24280356, 2013). "In this study, we reveal that Ets-1 elevates cellular glutathione levels in ovarian cancer cells, which could account for the therapeutic resistance associated with this transcription factor." (PMID 24238102, 2013). "Therefore, further examination of the regulation of Ets-1 and the functional consequences of its overexpression are of particular interest to the development of novel therapeutic approaches for ovarian cancer." (PMID 24238102, 2013). "Ovarian cancer cells that overexpress Ets-1 display a more active glutathione antioxidant system, a characteristic that could account for the chemotherapeutic resistance previously observed in these cells." (PMID 24238102, 2013). "Therefore, we suggest that under basal conditions ovarian cancer cells rely predominantly on the transsulfuration pathway to maintain GSH levels irrespectively of Ets-1 expression level." (PMID 24238102, 2013). "Recently, our laboratory showed the importance of Ets-1 as a regulator of cellular metabolism in ovarian cancer cells, where Ets-1 overexpression resulted in increased glycolysis while suppressing oxidative phosphorylation, a phenomena known as the Warburg effect." (PMID 24280356, 2013). "Beyond prostate cancer and Ewing sarcoma, PARP-1 inhibitors could be used to selectively kill Ets-1-expressing tumours in numerous cancers such as breast, lung, colorectal or ovarian carcinomas." (PMID 23405229, 2013). "To provide some validation for this finding, we examined the protein expression of elevated targets involved in the regulation of cellular redox status, and measured intracellular reactive oxygen species (ROS) production in ovarian cancer cells overexpressing Ets-1." (PMID 24280356, 2013). "Thus, the consequences of Ets-1 overexpression are particularly relevant to the study of ovarian cancer as this type of malignancy is very difficult to detect, and is most commonly diagnosed at advanced stages of disease progression that include metastases." (PMID 24280356, 2013). "In this study we have identified a role for proto-oncogene Ets-1 in the regulation of intracellular glutathione levels, and examined the effects of the anti-inflammatory drug sulfasalazine on glutathione depletion using an ovarian cancer cell model." (PMID 24238102, 2013). "We used immunohistochemistry (IHC) to detect the expression of Ets-1, angiopoietin-2 (Ang-2) and maspin in ovarian tumor and analyzed the relationship between the expression of these proteins and the clinical manifestation of ovarian cancer." (PMID 21439064, 2011). "The expression of Ets-1 was much stronger in ovarian cancer than benign tumors (p = 0.022)." (PMID 21439064, 2011).
ovarian carcinoma (continued). "Furthermore, Ets-1 has been suggested as a prognostic factor for ovarian cancer since there was a significant correlation between microvessel counts, survival rate and Ets-1 level in ovarian cancer." (PMID 21439064, 2011). "Consistent with our hypothesis, in this study we found that Ets-1 had a much stronger expression in ovarian cancer than in benign tumor (p = 0.022), suggesting that Ets-1 is a potential factor that contributes to ovarian cancer angiogenesis." (PMID 21439064, 2011). "Additionally, the Ets-1 over-expressing ovarian cancer cells displayed significantly decreased growth following glucose deprivation, further emphasizing their glycolytic reliance." (PMID 21042593, 2010). "Interestingly, Ets-1 was also found to be involved in the regulation of increased FASN gene expression in our ovarian cancer model." (PMID 21042593, 2010). "Using high throughput genomic analysis, we have found that Ets-1 regulates, either directly or indirectly, several important genes involved in mitochondrial metabolic and antioxidant defense pathways in our Ets-1 over-expression ovarian cancer cell model." (PMID 21042593, 2010). "Given that Ets‐1 is known to be overexpressed in ovarian cancer and has been suggested as a poor prognostic factor, it seems reasonable to speculate that the oxidative stress‐mediated antitumor effect, observed after PARP‐1 inhibition, is the result of the transcriptional activity of Ets‐1." (PMID 39778077, 2025). "Our results demonstrate the important role of laminins in exosomes generated from ETS1-overexpressing ovarian cancer cells in tumor progression by remodeling the tumor microenvironment and provide novel insights that may be useful in the treatment of omental metastasis in ovarian cancer." (PMID 36477408, 2022). "Therefore, we investigated the influence of ETS1 on tumor-derived exosomes secretion and content composition by regulating the expression of ETS1 in ovarian cancer cells and explored the impact of ETS1-mediated tumor-derived exosomes on omental metastasis in ovarian cancer." (PMID 36477408, 2022). "However, it remains unknown whether ETS1 can influence the metastasis of ovarian cancer by modulating exosome secretion and the content composition of tumor cells." (PMID 36477408, 2022). "However, the effects of ETS1 on the release and composition of exosomes derived from ovarian cancer cells remain unknown." (PMID 36477408, 2022). "Therefore, we speculate that miR-206/ETS1 regulates KRT80 to mediate the progression of ovarian cancer through the MEK/ERK pathway." (PMID 34659572, 2021). "Notably, we also observed an endogenous ETS1-GSK3β complex in ovarian cancer cell line." (PMID 34023818, 2021). "Therefore, HIF‐1α is a critical regulator of ETS‐1 expression under LPA exposure in ovarian cancer." (PMID 28236660, 2017). "Comparing the transcriptional programs of cancer cells that express low levels of Ets-1 protein to those that express Ets-1 protein in abundance will create a gene expression profile illustrating some of the key differences between invasive and non-invasive ovarian cancer cells." (PMID 24280356, 2013). "Thus we hypothesized that Ets-1 expression may be upregulated in ovarian cancer and contribute to ovarian cancer development." (PMID 21439064, 2011). "Interestingly, our findings suggest that Ets-1 could act as a transcriptional repressor of more than half of these genes in ovarian carcinoma cells." (PMID 21042593, 2010). "Our data proved that HMGB3 activates MAPK/ERK signaling in ovarian cancer, as indicated by increased MEK1/2 and ERK1/2 phosphorylation, and the upregulation of its downstream molecules, including ETS-1, CCND1, and c-Myc." (PMID 37328851, 2023). "Our data also showed that HMGB3 suppression reduces the expression of major downstream target genes of the MAPK/ERK signaling pathway, including ETS-1, CCND1, and c-Myc, which have key roles in ovarian cancer occurrence and development." (PMID 37328851, 2023).
ovarian carcinoma (continued). "According to qRT-PCR and western blotting data, ETS1 regulated the expression of LAMA5, LAMB1, and LAMC1 in ovarian cancer cells." (PMID 36477408, 2022). "In ovarian cancer samples from the TCGA database, the expression levels of LAMA5, LAMB1, and LAMC1 were positively correlated with that of ETS1." (PMID 36477408, 2022). "The results show that ETS1 transcriptionally regulates the expression of LAMA5, LAMB1, and LAMC1 in ovarian cancer cells." (PMID 36477408, 2022). "Because we have previously shown that LY2090314 can inhibit murine ovarian cancer-MOSEC cells growth, we also examined the endogenous ETS1 and MMP-9 protein levels in the same experimental tumors of LY2090314-treated mice." (PMID 34023818, 2021). "In ovarian cancer, VEGF induces ETS1 expression by activating the PI3K/Akt and p38MAPK signaling pathways, which further activates MMP9 and MMP13 and promotes SKOV3 invasion and metastasis." (PMID 34659572, 2021). "Here, we report the transcriptional induction of ETS‐1 upon direct binding to its promoter through HIF‐1α in both HIF‐1α‐overexpressed cells and LPA‐induced ovarian cancer cells." (PMID 28236660, 2017). "The functional significance of ETS‐1 was further investigated by assessing the effect of its knockdown on the LPA‐induced invasion and migration of ovarian cancer cells." (PMID 28236660, 2017). "ETS1 is found to be co-expressed with MMP-1 and MMP-9 in angiosarcoma of the skin, ovarial carcinoma cells and stromal fibroblasts in breast and ovarian cancer." (PMID 26177288, 2015). "Considering these results, further investigation into the interrelationship between Ets-1, Nrf2, and HIF-1α in ovarian cancer cells is warranted." (PMID 24238102, 2013). "Therefore, we speculated that the reason for negative or weak positive expression of maspin in ovarian cancer was due to the dysfunction of Ets-1 which downregulated maspin expression at transcription level although the expression of Ets-1 was much stronger in ovarian cancer than benign tumors." (PMID 21439064, 2011). "Additionally, ETS1, a key regulator of epithelial-mesenchymal transition (EMT) and metastasis in ovarian cancer cells, is also modulated by Gln." (PMID 40276500, 2025). "By integrating the GSE26712, GSE18520, GSE105437, GSE14407, and other datasets, we further confirmed that ETS1 expression was higher in ovarian cancer tissues than in normal tissues." (PMID 36477408, 2022). "Interestingly, H2O2 upregulates Ets-1, a member of ETS proteins family, expression in both OV2008 and C13 ovarian carcinoma cell lines." (PMID 35453348, 2022). "ETS1 overexpression altered the size of exosomes derived from ovarian cancer cells, and upregulated the expression of three laminins, LAMA5, LAMB1, and LAMC1, in ovarian cancer cells and their exosomes." (PMID 36477408, 2022). "We also analyzed phospho-ETS1 and MMP-9 in ovarian cancer tissues." (PMID 34023818, 2021). "Ets-1 was over-expressed using a stably-incorporated tetracycline-inducible expression vector in the ovarian cancer cell line 2008, which does not express detectable basal levels of Ets-1 protein." (PMID 21042593, 2010). "Some studies had found that ETS1 exosomes secreted by ovarian cancer cells induce the polarization of M2 macrophages, which overexpress CD163, IL-10, CCL2, CXCL5 and other immunosuppressive factors, and significantly stimulate the migration of ovarian cancer cells." (PMID 39539540, 2024). "Nevertheless, according to an integrated survival analysis of the GEO datasets and the TCGA ovarian cancer cohort, ETS1 mRNA may not be a reliable indicator of ovarian cancer patients." (PMID 36477408, 2022). "Notably, we observed that H3K9ac deletion and/or ETS1 enrichment were effective ways to induce a decrease of PARP1 levels in SKOV3 cells and primary non-mutated and BRCA1-mutated ovarian cancer cells (Fig. 3Ei-Eiv)." (PMID 24448423, 2014).